MTOR (mechanistic target of rapamycin kinase)
Diseases named in the same sentence as MTOR in open-access papers (continued):
Sharing a sentence is not in itself a finding about the gene and the disease.
tumor (continued). "In line with this evidence, the treatment with PD-L1 blocking antibodies suppressed tumor progression and glucose uptake in tumor cells while enhancing mTOR activity of T cells." (PMID 33418913, 2021). "Activation of upstream PI3K/AKT signaling further activates mTOR to promote the growth and division of tumor cells by inducing microtubule growth and other activities." (PMID 34823532, 2021). "Taking into account that inositol pathway dysregulation, through IP6 treatment, inhibits mTOR pathway activation and the metabolic adaptation mediated by the signature in G4 MB cells, we set out to assess their impact on tumour cell viability." (PMID 33846320, 2021). "Overall, the pharmaceutical inhibition of mTOR signaling by rapamycin not only inhibits tumor development but also promotes the reductive effect of γ-radiation on tumor volumes." (PMID 33959512, 2021). "Activated mTOR provides tumor cells with a significant survival and growth advantage, owing to enhanced protein synthesis, decreased autophagy, and apoptosis." (PMID 34833123, 2021). "The ketogenic diet can also suppress the mTOR signaling pathway, reducing inflammation and significantly reducing tumor growth." (PMID 33918992, 2021). "Previous reports have suggested that GALNT7 is involved in the regulation of tumor progression through PI3K/Akt/mTOR and EGFR/PI3K/AKT pathways." (PMID 34819077, 2021). "And E-cadherin’s downstream effector molecules related to RAS and RAF/MEK pathways and other tumor-forming pathways such as FAK/C-SRC and PI3K/AKT/mTOR pathways, thus contributing to tumor cell proliferation and metasitasis." (PMID 34422902, 2021). "This special phenomenon once again illustrates that mTOR plays different roles in different stages of tumor development through the degree of activation." (PMID 34194607, 2021). "IGF-1R, EGFR, and VEGF can bind to RTKs, which will activate RAS-RAF-MAPK and PI3K/AKT/mTOR signaling pathways, promoting tumor growth, progression, cell survival, motility, and invasion." (PMID 34638601, 2021). "Previously, we have demonstrated that Urolithin A mediated simultaneous targeting of the PI3K/Akt/mTOR pathway reduced PDAC tumor growth and improved survival in the genetically engineered mouse model (GEMM) of PDAC." (PMID 34503244, 2021). "MLN4924 was found to trigger epidermal growth factor receptor (EGFR) dimerization and activate EGFR downstream signaling pathways such as RAS/RAF/MEK/ERK and PI3K/AKT1/mTOR promoting tumor sphere formation and inducing wound healing in mouse models." (PMID 33572115, 2021). "The PI3K/AKT/mTOR signaling pathway in tumor cells is further activated by radiation, resulting in tumorigenesis, progression, angiogenesis, invasion, metastasis, and anti-apoptosis." (PMID 34665844, 2021). "Regarding the potential mechanisms of glycolysis in CRC cells, an increasing number of studies found that activation of the mTOR pathway directly correlates with increased glycolysis in tumor cells compared with normal cells." (PMID 33791391, 2021). "Meanwhile, the mTOR signaling is also involved in immune checkpoint expression and downstream signaling in tumor cells and immune cells." (PMID 34858835, 2021). "By examining the whole exome sequencing of this patient, it was observed that the tumor presented missense mutations in the fibroblast growth factor receptor 2 (FGFR2) and mammalian target of rapamycin (mTOR) genes." (PMID 34358097, 2021). "For instance, SNHG3 is a novel lncRNA that has been identified to have a tumor-suppressor function during papillary thyroid carcinoma (PTC) development, and its silencing can activate tumor progression by modifying the AKT/mTOR/ERK signaling pathway." (PMID 34885213, 2021). "The abnormal activation of AKT/mTOR signaling pathway can accelerate the proliferation of tumor cells, enhance resistance to apoptosis, and promote tumor invasion and metastasis." (PMID 34953496, 2021).
tumor (continued). "The PI3K/Akt/mTOR axis constitutes a crucial pathway regulating a plethora of biological processes involved in tumor development, such as angiogenesis, proliferation, metabolism, survival, and differentiation." (PMID 34681797, 2021). "After the inclusion of miR-199a-3p, exosomes secreted by ADSCs (ADSC-exo-199a) effectively targeted mammalian target of rapamycin (mTOR), which increased the sensitivity of tumors to chemotherapeutic drugs and significantly reduced the tumor volume." (PMID 34142930, 2021). "Others have found that the combination of mammalian target of rapamycin (mTOR) inhibitors with radiotherapy and caspase inhibitors results in a potent anti-tumor effect due to an increase of autophagic TCD." (PMID 34141622, 2021). "Taken together, these findings indicate that a complex FoxP3-miR-150-IGF1R/IRS1-PI3K/AKT/mTOR feedback loop regulates OC pathogenesis, providing a novel mechanism for miR-150 as a tumor suppressor miRNA in OC." (PMID 33723215, 2021). "EIF4EBP1 (4E-BP1) is an important downstream target of mTOR and controls the mRNA translation of many tumor progression-related genes." (PMID 34953500, 2021). "Given that HMB indirectly promotes mTOR activation via a number of mechanisms, we assessed tumor mTOR activity." (PMID 34944981, 2021). "Other groups have reported that mTOR inhibition increases GLS expression, thus increasing tumor dependency on glutamine as a potential resistance mechanism to mTOR inhibition." (PMID 34731180, 2021). "Both PI3K and mTOR inhibitors have been shown to enhance the efficacies of targeted immunotherapies in mouse tumor xenotransplantation models." (PMID 34916492, 2021). "One proposed mechanism by which dormancy confers chemotherapeutic resistance is that stromal cells can induce expression of TBK1, which has been shown in PC3 and C4-2B tumor cells to promote chemotherapeutic resistance via inhibition of mTOR." (PMID 33805598, 2021). "As the most important downstream signal molecule of PI3K/Akt, mTOR is activated by Akt phosphorylation, and the expression of mTOR is abnormally increased in tumor progression." (PMID 33865336, 2021). "Among them, the AKT1/mTOR axis is a classic metabolic pathway required to sustain tumour metabolic homeostasis." (PMID 34898043, 2021). "Rapamycin and 3BDO, as pharmaceutical regulators of mTOR activation, worked effectively in tumor tissues." (PMID 33959512, 2021). "PI3K/AKT/mTOR pathway plays many important roles in tumor cell proliferation, survival, differentiation, invasion, migration, and metastasis." (PMID 34789718, 2021). "In summary, apigenin affects the PI3K/AKT/mTOR signaling pathway by regulating the expression level of ERα/ERβ, thereby decelerating tumor development promoted by histamine." (PMID 34568014, 2021). "mTOR signaling regulated by LAT1 is a sensor of dynamic alterations in the nutrient tumor microenvironment." (PMID 33401672, 2021). "AMPK inhibits the phosphorylation of the mTOR complex and its downstream molecules through various molecular mechanisms, thereby reducing the progression and metastasis of tumor cells." (PMID 33816275, 2021). "Together with the observation that mTOR inhibitors are able to restore nucleophagy and to reduce tumour growth in vivo, these findings suggest that nucleophagy needs to be upregulated in order to lower the tumorigenic potential of ependymoma." (PMID 33803216, 2021). "These are accomplished through interfering signaling cascades, resulting in mTOR activation pertinent to tumor survival and progression." (PMID 34207850, 2021). "In the connecting molecular mechanism between ATP depletion and tumor regression, mTOR was the key master regulated by ATP level that command biogenesis, adipogenesis, and angiogenesis." (PMID 33537098, 2021). "In conclusion, above findings suggest that lomerizine 2HCl markedly suppresses the growth of tumor in vivo by suppressing the PI3K/AKT/mTOR signaling pathway, which is consistent with the results observed in vitro." (PMID 34766155, 2021).
tumor (continued). "Many studies have shown that induction of miR-96 can regulate downstream mTOR, thereby promoting tumor metastasis." (PMID 35047559, 2021). "Tumor cells utilize glucose and metabolically compete with T cells through impairing mammalian target of rapamycin (mTOR) activity and glycolytic activity in T cells, leading to the overriding of the capability of T cell-mediated cytotoxicity." (PMID 33627136, 2021). "Through inhibition of glucose uptake, EGFR TKI triggered AMPK activation in an LKB1-dependent manner due to the reduction of ATP level to suppress mTOR signaling and tumor growth." (PMID 33335306, 2021). "The mTOR pathway can directly act on the energy metabolism of tumor cells, or it can play a role by affecting immune cells." (PMID 33546704, 2021). "This study reveals tumor regulatory functions for essential components of the mTOR and Hippo pathways in TNBC." (PMID 34031411, 2021). "The mammalian target of rapamycin (mTOR) strongly engages in various tumor progression processes by activating the signaling pathway PI3K/Akt." (PMID 34221232, 2021). "In this study, gene set enrichment analysis showed that the mTOR pathway, a central pathway in tumor initiation and progression, was significantly enriched in the high‐risk group." (PMID 34581026, 2021). "Rapamycin is a highly specific inhibitor of mTOR and potently suppresses tumor cell growth by retarding cells in G1 phase or potentially inducing apoptosis." (PMID 33771193, 2021). "Complexes formed between FKBPs and their ligands regulate cell signaling pathways, including the mechanistic target of rapamycin (mTOR), and hyperactivation of this molecule is known to play a role in tumor transformation and growth." (PMID 34454589, 2021). "ccRCC is an immunotherapy-sensitive tumor, and mTOR regulates tumor immunity (Posadas, Limvorasak & Figlin, 2017; Saxton & Sabatini, 2017)." (PMID 34458019, 2021). "The biological rationale of this combination strategy is to be found in the mTOR pathway activation after the tumor hypoxia induced by VEGF-targeting treatments." (PMID 34207825, 2021). "PDCD4 is involved in apoptosis and inhibits tumor progression by acting on eIF4A and eIF4G, suppressing mRNA translation whereas PTEN diminishes the P13K/Akt/mTOR signaling pathway which results in tumor growth." (PMID 33768115, 2021). "The PI3K/Akt/mTOR pathway is analogous with cell growth, development, proliferation, metastasis, malignant transformations, tumor progression, therapeutic resistance, and apoptosis." (PMID 34452154, 2021). "By converting TRP to KYN, MSCs-sourced IDO induces low TRP levels, activates GCN2 kinase and suppresses PKB/mTOR signaling in tumor-infiltrating Tregs, preventing their trans-differentiation in anti-tumorigenic Th17-like cells." (PMID 34830312, 2021). "The induced reversible anti-proliferative, anti-tumour growth effects and sensitisation of different chemotherapeutics after rapalog treatment were described in our previous in vitro mTOR inhibitor studies." (PMID 34360785, 2021). "At the same time, the induction of p-mTOR is closely related to tumor invasion, tumor stage and low survival." (PMID 34488535, 2021). "Lactate contributes to one mechanism of radioresistance in pancreatic cancer by enhancing the tumor-promoting activity of MDSCs via the GPR81/mTOR/HIF1α/STAT3 pathway." (PMID 33923299, 2021). "Both mTOR signalling and inositol contribute to the modulation of energy production which is crucial for the tumour to functionally adapt to a high proliferative state." (PMID 33846320, 2021). "In many tumor studies, inhibition of mTOR signaling has been shown to improve the efficacy of radiotherapy." (PMID 33959512, 2021). "A high expression of mTOR in HNSCC is found to be related to perineural invasion in the tumor and a poorer prognosis compared to cases with low expression." (PMID 33802643, 2021). "At the same time, studies have shown that targeting PI3K/AKT/mTOR-mediated autophagy can inhibit tumor growth." (PMID 34203270, 2021).
tumor (continued). "mTOR signalling is one of the major hubs of the glucose‐sensing pathway, and large amounts of glucose are essential for tumour progression." (PMID 34954904, 2021). "Based on our analysis, we suggest that SIRT1 has a tumor suppressing role in mTOR-driven HCC tumors." (PMID 34348664, 2021). "Deregulation of mTOR signaling correlates with tumor progression and poor outcome in patients with ccRCC." (PMID 34290272, 2021). "In a mouse sarcoma model, it has been demonstrated that increased glycolysis and thus glucose consumption in tumor cells metabolically restricts T lymphocytes by reducing mTOR activity, glycolytic capacity, and interferon (IFN)-γ production in these cells." (PMID 34073734, 2021). "Our previous work has demonstrated that targeting the PI3K/Akt/mTOR pathway reduced tumor growth and improved survival in the genetic mouse model of PDAC." (PMID 34503244, 2021). "Immunohistochemistry analysis of phospho rpS6 in the tumour region shows a reduction consistent with mTOR inhibition." (PMID 34389715, 2021). "Our study showed that the overexpression of miR-124-3p affected tumor progression in NPC cells through the PI3K/AKT/mTOR pathway." (PMID 34234863, 2021). "The mechanistic target of rapamycin (mTOR) pathway plays a critical role in tumor survival, metabolism, and proliferation." (PMID 34067530, 2021). "Initial studies into mTOR as a target for tumor radiosensitization utilized rapamycin and its derivatives, which are allosteric mTOR inhibitors." (PMID 34639005, 2021). "In 17 patients, ETA also identified other tumor features such as (but not limited to) activation of mTOR or hormone receptor signalling pathways." (PMID 39087078, 2021). "PTEN, a tumor suppressor gene, is a negative regulator of the PI3K/mTOR pathway, and abnormal activation of the PI3K/mTOR pathway has been associated with the development of malignancies, including BTC." (PMID 34316332, 2021). "Then we further investigated the role of mTOR (including p-mTOR) on tumor prognosis using Cox regression analysis." (PMID 34458019, 2021). "Immunosuppressor rapamycin inhibits tumor progression by targeting mammalian target of rapamycin (mTOR)." (PMID 34899336, 2021). "Additional studies with other ATP competitive mTOR inhibitors support mTORC1/2 as a target for tumor cell radiosensitization." (PMID 34639005, 2021). "Tumor cell‐intrinsic PD‐L1 signals modulate mTOR, autophagy, growth, metastasis, treatment resistance (e.g., small molecules, chemotherapy, immunotherapy), epithelial‐to‐mesenchymal transition, and DNA damage repair in these various tumor cells." (PMID 33626233, 2021). "A composite “mTOR activity” score, determined from the average distribution score of these phosphorylation biomarkers, was grouped based on in vivo tumor growth inhibition." (PMID 34900714, 2021). "PIK3CA activating mutations lead to hyperactive signaling downstream of mTORC1, and suggest a tumor-promoting function for mTOR signaling in TNBC25." (PMID 34031411, 2021). "Downregulation of AMPK by MAGEA6 led to significant decrease in autophagy and upregulation of mTOR, facilitating tumor growth." (PMID 34885040, 2021). "In this review, we focus on the current understanding of PI3K/AKT/mTOR signaling in tumor development." (PMID 34279440, 2021). "SREBP1c, which is the major factor upstream of FASN, is usually activated by the AKT/mTOR signaling pathway and plays an important role in tumor cell survival and progression." (PMID 34158007, 2021).
tumor (continued). "Differentiation is usually mediated by tumor-derived lactate via Akt/mTOR signaling pathway affecting the expression of pro-inflammatory cytokines and chemokines, Arg1, IL4Ra, and epithelial-to-mesenchymal transition (EMT)." (PMID 33670011, 2021). "Previous studies postulated that MACC1 controls PDL1 expression and tumor immunity by modulation of the c-Met/AKT/mTOR pathway, hence affecting cytotoxic T-cells in BC TME." (PMID 34577857, 2021). "Conversely, inhibitors targeting PI3K, Akt, or mTOR, either used alone or in combination, impede pNET cell growth and tumor development and metastasis in mice, suggesting pNET cells require Akt-mTOR signaling for their survival, growth, and migration." (PMID 34680266, 2021). "STAT3 is essential for mesenchymal transformation and tumor aggressiveness and is considered as a downstream pathway of mTOR signaling." (PMID 34771718, 2021). "Despite the metabolic functions, PKM2 inhibits mTOR-mediated tumor progression, and also it is involved in cell cycle regulation and drug resistance." (PMID 33827418, 2021). "Its silence can promote apoptosis autophagy and inhibit the proliferation, migration, and invasion of tumor cells through the mTOR signaling pathway." (PMID 33910497, 2021). "By integrating proteomic and transcriptomics profiles of GC and PM samples, we reported that APOC2 cooperated with CD36 to regulate EMT process via PI3K/AKT/mTOR signaling, which eventually promoted tumor progression and PM in GC." (PMID 34459127, 2021). "SET domain bifurcated 1 (SETDB1) is upregulated in GBM and promotes AKT/mTOR-dependent CSF-1 induction and secretion, which leads to macrophage recruitment in the tumor, resulting in tumor growth." (PMID 34071306, 2021). "Whole-genome RNA sequencing (RNA-Seq) transcriptomes and reverse-phase protein array (RPPA) proteome analyses revealed that ERα and mammalian target of rapamycin (mTOR) signaling predominantly regulate tumor growth of SC31." (PMID 34944995, 2021). "The protein level of mTOR and p-mTOR was determined by western blotting (WB), and their expression was evaluated in 145 ccRCC and 13 non-tumor specimens by immunohistochemistry (IHC)." (PMID 34458019, 2021). "mTOR inhibitors can effectively inhibit tumor proliferation and angiogenesis in RCC and are recommended as second-line therapies for patients with mRCC." (PMID 33746989, 2021). "We identify the oncogenic mTOR and tumor-suppressive Hippo signaling pathways as central regulators of tumorigenesis in TNBC." (PMID 34031411, 2021). "The high tumor burden observed in our study makes the PI3K/mTOR signaling pathway an interesting potential druggable target for patients with KRAS A146–mutated tumors." (PMID 34820593, 2021). "Activated Akt further induces the mTOR pathway, leading to cell proliferation and protein synthesis in tumor cells." (PMID 33842335, 2021). "In conclusion, our results suggest that activation of mTOR signalling is required for EIF4G1‐induced tumour growth in NSCLC." (PMID 33523588, 2021). "When IGF-1R is combined with its ligand, it can activate the PI3K/Akt/mTOR signaling pathway, and play an important role in the proliferation and apoptosis of tumor cells." (PMID 33996542, 2021). "The PI3K/AKT/mTOR pathway has been shown in many types of cells including tumor cells, endothelial cells and MSCs to regulate cell functions like proliferation, angiogenesis, viability and cell migration." (PMID 34837694, 2021). "ULK1/2 has been linked to diverse oncogenic or tumor-suppressive signalling cascades (e.g., KRASG12D/Copper, PI3K/AKT/mTOR, FAK/RhoA, STK11/liver kinase-B1 [LKB1]) that are engaged in pathogenesis of solid tumors from various types 50-52." (PMID 34345207, 2021). "The data indicated that autophagy restraint contributed to the tumor suppression by BO, which is possibly mediated by the mTOR activation via amino acid metabolism regulation." (PMID 34658867, 2021).